GCG (glucagon)
Diseases named in the same sentence as GCG in open-access papers (continued):
Sharing a sentence is not in itself a finding about the gene and the disease.
adenoma (6 papers, 2010 to 2024). A neoplasm arising from the epithelium. "A previous study demonstrated that GCG was constantly down-regulated in adenomas in comparison with the gene expression level in normal colorectal mucosa." (PMID 32508878, 2020). "Furthermore, among the eight individuals studied, three presented with adenomas smaller than 1 cm and 1 had an adenoma ≥ 1 cm, the majority of which stained positive for glucagon." (PMID 39309109, 2024). "Moreover, CA1, CHGA, and GCG decreased significantly from normal to adenoma and continued to decrease significantly from adenoma to carcinoma, indicating that these genes continued to play a role in inhibiting the process from normal to adenoma then to carcinoma." (PMID 36944972, 2023). "In case of two genes, GCG and NMES-1, a remarkable decrease was found in the gene expression already in the adenoma stage." (PMID 23049694, 2012). "Results showed good agreement with the microarray analysis, GCG, NMES-1, and FAM161B genes were downregulated in both the adenoma and the tumor samples, while LRMP showed reduced expression only in the tumor samples." (PMID 23049694, 2012).
Cachexia (6 papers, 2014 to 2023). Severe weight loss, wasting of muscle, loss of appetite, and general debility related to a chronic disease. "However, there are several diseases states, such as infection or chronic heart failure, in which elevated glucagon is associated with decreased food intake and cachexia." (PMID 26909312, 2015). "The stark rise of glucagon may even contribute to the development of the wasting syndrome through its central anorexigenic effects." (PMID 25119860, 2014). "Notable increases in ghrelin and glucagon occurred in TCDD-treated Long-Evans rats alone, which links these hormones to the wasting syndrome." (PMID 25119860, 2014). "There are also differences in insulin sensitivity between cancer patients with or without associated cachexia, due to hormonal imbalances (vitamin D, testosterone, GLP-1, glucagon, ghrelin, apelin) and adipose tissue modifications." (PMID 38067294, 2023). "To determine whether the model of LPS-induced cachexia is established, we initially examined the concentrations of several blood markers of cachexia including plasma insulin (INS), growth hormone (GH), cortisol (COR), and glucagon (GLU)." (PMID 37446099, 2023).
gestational diabetes (6 papers, 2019 to 2025). Carbohydrate intolerance first diagnosed during pregnancy. "The gene EGR1 promotes the development of gestational diabetes by adversely impacting the glucagon-controlled gluconeogenesis." (PMID 30755828, 2019). "This was also observed with glucagon, where FABP4 promotes hepatic glucose production irrespective of insulin, particularly in women with gestational diabetes mellitus (GDM)." (PMID 38731797, 2024).
hyperinsulinemic hypoglycemia (6 papers, 2020 to 2026). An inherited autosomal recessive syndrome characterized by the disorganized formation of new islets in the pancreas and congenital hyperinsulinism. "Our results indicate that it is possible to overcome these glucagon inhibitory signals and to alleviate hyperinsulinemic hypoglycemia by amplifying glucagon signaling downstream of the initiating glucagon receptor binding." (PMID 32735622, 2020). "Critical sampling demonstrated inappropriately detectable insulin and C-peptide, absent ketonuria, suppressed β-hydroxybutyrate, and a diagnostically significant glycemic response to glucagon, confirming hyperinsulinemic hypoglycemia (HH) consistent with congenital hyperinsulinism (CHI)." (PMID 42220696, 2026).
ischemic stroke (6 papers, 2021 to 2024). A stroke disorder caused by obstruction of blood flow to the brain, due to thrombotic (local blood clot formation) or embolic (due to a blood clot or other material traveling from another site) event. "These can be explained by the increased levels of cortisol, plasma endothelin, and glucagon, which lead to internal environment imbalance and lower plasma [Mg2+] levels, contributing to a higher risk of ischemic stroke." (PMID 35345487, 2022).
liver cirrhosis (6 papers, 2012 to 2025). "Thyroid hormone concentration is also affected by glucagon levels and, in liver cirrhosis, plasma glucagon concentration is frequently elevated." (PMID 22919507, 2012). "On the other hand, HGF and glucagon are higher only in T2D patients and this confirms that glucagon and HGF play a specific role in glucose production and homeostasis and in the progression of chronic inflammation to liver cirrhosis and cancer, respectively." (PMID 22745767, 2012).
prostate carcinoma (6 papers, 2021 to 2026). A carcinoma that arises from epithelial cells of the prostate gland. "And for KEGG analysis, the top five descriptions were prostate cancer (hsa05215), the insulin signaling pathway (hsa04910), small-cell lung cancer (hsa05222), the adipocytokine signaling pathway (hsa04920), and the glucagon signaling pathway (hsa04922)." (PMID 34540994, 2021).
renal dysfunction (6 papers, 2016 to 2026). "The kidneys are known to play an important role in the clearance of glucagon, and in previous reports as well, renal dysfunction was shown to be correlated with elevated plasma glucagon levels." (PMID 41292690, 2026).
sarcopenia (6 papers, 2021 to 2025). Progressive decline in muscle mass due to aging which results in decreased functional capacity of muscles. "An extreme example of the effects of GCG on lean mass is in individuals with glucagonoma, which is characterised by very high levels of circulating GCG, low levels of amino-acids, and sarcopenia." (PMID 40741227, 2025).
Arrhythmia (5 papers, 2018 to 2026). Any cardiac rhythm other than the normal sinus rhythm. "In contrast, at least one report concluded that, even in healthy volunteers, glucagon infusion could induce arrhythmias." (PMID 37629010, 2023). "In dogs, glucagon effectively treated ouabain-induced cardiac arrhythmias." (PMID 37629010, 2023).
cardiac arrest (5 papers, 2016 to 2025). Cessation of breathing and/or cardiac function. "According to current guidelines, further escalation of adrenaline, consideration of vasopressin or glucagon, and the initiation of extracorporeal life support in the event of recurrent cardiac arrest would be appropriate." (PMID 41458793, 2025).
dilated cardiomyopathy (5 papers, 2014 to 2023). Cardiomyopathy which is characterized by dilation and contractile dysfunction of the left and right ventricles. "KEGG analysis showed that these genes were enriched in adrenergic signaling in cardiomyocytes, cardiac muscle contraction, hypertrophic cardiomyopathy, dilated cardiomyopathy, and glucagon signaling." (PMID 37601265, 2023). "Other biologically relevant functions related to behavior, but that were non-significant, were metalloprotease, neuroactive ligand–receptor interaction, dilated cardiomyopathy, and hormone signaling pathway (e.g., GnRH, aldosterone, oxytocin, estrogen, glucagon, and dopamine hormones)." (PMID 33800722, 2021).
gastroparesis (5 papers, 2017 to 2024). Paralysis of the muscles of the stomach wall resulting in delayed emptying of the gastric contents into the small intestine. "We would have to be very cautious though in introducing such enhancers, since slow-wave velocity has been reported to be already highly elevated in the gastric corpus of aged patients having gastroparesis with impaired peristalsis and somewhat elevated in glucagon induced hyperglycemic dogs." (PMID 34871315, 2021). "For people with gastroparesis,side effects of glucagon and pramlintide which include nausea, vomiting andearly satiety may be particularly troublesome." (PMID 34378426, 2021).
hypertrophic cardiomyopathy (5 papers, 2020 to 2023). A condition in which the myocardium is hypertrophied without an obvious cause. "KEGG was enriched in hypertrophic cardiomyopathy, the glucagon signaling pathway, cardiac muscle contraction, adrenergic signaling in cardiomyocytes, and other pathways related to the regulation of cardiomyocytes." (PMID 32724326, 2020). "KEGG pathway is enriched in oxytocin signaling pathway, circadian rhythm, hypertrophic cardiomyopathy (HCM), glucagon signaling pathway, cardiac muscle contraction, adrenergic signaling in cardiomyocytes, influenza A, hepatitis C, herpes simplex infection, and glycolysis." (PMID 32724326, 2020).
Hypokalemia (5 papers, 2008 to 2025). An abnormally decreased potassium concentration in the blood. "When hypotension does not improve with intravenous calcium and vasoactive drugs, glucagon may be used due to its ability to increase cardiac contractility and improve blood pressure; however, its use is limited by common side effects, including nausea, vomiting, ileus, and hypokalemia." (PMID 41141045, 2025).
malaria (5 papers, 2016 to 2023). Malaria is a serious and sometimes fatal disease caused by a parasite that commonly infects a certain type of mosquito which feeds on humans. "In all patients with malaria, total cortisol levels correlated with parasitemia (Spearman r = 0.41, p = 0.004), glucagon (Spearman r = 0.30, p = 0.038) and lactate levels (Spearman r = 0.3140, p = 0.0316), suggesting a link between cortisol responses and other malaria-associated disturbances." (PMID 37492570, 2023). "In addition, it is important to note that neither the high glucagon levels nor DEX treatment of infected Adx mice were able to induce the transcription of these genes, suggesting that malaria-infection severely compromises the induction of their expression." (PMID 30375380, 2018).
MODY (5 papers, 2018 to 2024). "We found that insulin suppression and glucagon release occur at a higher glucose levels in GCK-MODY than T2D and that there is an exaggerated epinephrine response to glucose lowering in GCK-MODY." (PMID 30146176, 2018).
renal failure (5 papers, 2018 to 2025). "Furthermore, this animal exhibited signs of stress, evidenced by high plasma epinephrine and glucagon concentrations, prior to the insulin clamp in addition to renal failure." (PMID 30540820, 2018).
somatostatinoma (5 papers, 2017 to 2022). A rare, usually malignant neuroendocrine tumor arizing from delta cells. "In most patients (92.7%), the clinical somatostatinoma syndrome was caused by the inhibition of insulin, glucagon, gastrin, secretin, and somatotrophin." (PMID 33204258, 2020).
thyroid cancer (5 papers, 2017 to 2026). "Similarly, increased GCG expression is linked to improved survival in renal clear cell carcinoma, liver hepatocellular carcinoma, lung squamous cell carcinoma, and thyroid carcinoma." (PMID 39777709, 2025). "Conversely, higher GCG expression was correlated with better survival in renal clear cell carcinoma (HR = 0.43, logrank p < 0.001) and thyroid carcinoma (HR = 0.59, logrank p = 0.045), with a similar trend observed in renal papillary cell carcinoma (HR = 0.43, logrank p = 0.17)." (PMID 39777709, 2025).
viral infection (5 papers, 2015 to 2024). "Activated categories were dominated by Amino acid metabolism, Cardiovascular disease, Cell movement and survival, Connective tissue inflammation, Quantity of glucagon, Quantity of blood cells and leucocytes, RNA virus infection and Lipid metabolism." (PMID 36290086, 2022). "The gene network was significantly enriched with 51 KEGG pathways (FDR-p < 0.05) that predominantly consisted of signaling pathways, such as Wnt, cancer, Notch, thyroid hormone, TGF-β, glucagon, as well as adherens junction and viral infections (e.g., HTLV-1, herpesvirus, EBV, measles)." (PMID 39457448, 2024). "In contrast, α-cell-specific transcripts including GCG, ARX, BAMBI, DPP4, and POU6F2 were not affected by infection, which corresponded with our observation that viral infection was infrequent in α cells." (PMID 32093375, 2020).
acromegaly (4 papers, 2019 to 2025). Acromegaly is an acquired disorder related to excessive production of growth hormone (GH) and characterized by progressive somatic disfigurement (mainly involving the face and extremities) and systemic manifestations. "The fasting glucagon levels and its AUC at baseline were significantly higher in patients of acromegaly than the levels seen in healthy controls." (PMID 30948746, 2019). "The higher glucagon levels in patients of acromegaly could have possibly resulted from the direct cytotrophic effect of elevated GH/IGF-1 on pancreatic α-cells." (PMID 30948746, 2019). "While there are only a couple of studies investigating glucose-dependent insulinotropic polypeptide (GIP) and glucagon levels in acromegaly, there are no studies documenting the alterations in glucagon like peptide-1 (GLP-1) levels in patients with acromegaly." (PMID 30948746, 2019). "Hyperglucagonemia in patients of acromegaly and the lack of appropriate suppression of glucagon in post-prandial states is an outcome of exaggerated α-cell response to glucose and impaired insulin-mediated inhibition of α-cell through its paracrine action." (PMID 30948746, 2019). "However, when the data of all the patients of acromegaly were pooled together, there was a rank order correlation between GIP and glucagon levels (r 0.73, p < 0.001)." (PMID 30948746, 2019). "Failure of the GLP-1 levels to rise in patients of acromegaly, akin to GIP levels, can possibly be explained by the fact that GLP-1 is known to inhibit glucagon secretion and vice versa high levels of glucagon, seen in patients of acromegaly in our study, could have inhibited GLP-1 secretion." (PMID 30948746, 2019).
Adrenal insufficiency (4 papers, 2018 to 2025). Insufficient production of steroid hormones (primarily cortisol) by the adrenal glands. "Conversely, another study on 25 adult patients tested with glucagon reported abnormal reserve in one patient; however, the cut-off used to establish adrenal insufficiency was set at 599 nmol/l (21 μg/dl), thus some patients may have been missed." (PMID 29572711, 2018).
chronic heart failure (4 papers, 2010 to 2023). "Thus, glucagon induces an inotropic response in papillary muscles from patients with conserved cardiac function but not in those from patients with chronic heart failure." (PMID 37254135, 2023).
Cushing syndrome (4 papers, 2018 to 2025). Cushing's syndrome (CS) encompasses a group of hormonal disorders caused by prolonged and high exposure levels to glucocorticoids that can be of either endogenous (adrenal cortex production) or exogenous (iatrogenic) origin. "G-protein-coupled receptors responding to LH, glucose-dependent insulinotropic peptide (GIPR), serotonin, vasopressin, and glucagon have been identified in some humans with ACTH-independent Cushing's syndrome." (PMID 30356827, 2018).
cystic fibrosis (4 papers, 2017 to 2026). Autosomal recessive disorder caused by pathogenic variants in the CFTR gene (cystic fibrosis transmembrane conductance regulator), which encodes a chloride and bicarbonate channel expressed in epithelial cells, and follow the diagnosis criteria. "Associations between beta cell function and nadir concentration of glucagon in 87 adults with cystic fibrosis during a standard oral glucose tolerance test." (PMID 37720541, 2023). "CF is caused by a mutation in the Cl− channel Cystic fibrosis transmembrane conductance regulator (CFTR), but whether CFTR is present in human alpha cells and regulate glucagon secretion has not been investigated in detail." (PMID 28273890, 2017).
glucose metabolism disorders (4 papers, 2017 to 2024). "The present findings provide an alternative explanation for blood glucose metabolic disorder observed in PCOS via impaired glucagon production, as a result of hyperandrogenism-induced CFTR upregulation." (PMID 29204121, 2017).
glycogen storage disease (4 papers, 2011 to 2023). "Alternatively, a poor response to glucagon may be seen in glycogen storage diseases." (PMID 37404330, 2023).
hypercortisolism (4 papers, 2012 to 2025). "The metabolic effects of VP are mediated via the V1a receptor (V1aR) and V1b receptor (V1bR) and include gluconeogenesis and glycogenolysis, glucagon secretion, antilipolysis and hepatic production of triglycerides, and adrenocorticotropic hormone (ACTH) release and hypercortisolism." (PMID 35340071, 2022). "We conclude that efforts to abate the hypermetabolic, hypercatabolic response to stress must not exclusively address hypercortisolemia, but must inhibit the effects of catecholamines or other factors such as glucagon, either jointly or solely." (PMID 22606232, 2012).
lung carcinoma (4 papers, 2009 to 2025). "Significantly upregulated KEGG pathways among the top 10 metabolic pathways with the smallest p-values in the lung cancer group included: Alanine, aspartate, and glutamate metabolism, Biosynthesis of amino acids, Central carbon metabolism in cancer, TCA cycle, and Glucagon signaling pathway." (PMID 41311499, 2025).
Mahvash disease (4 papers, 2011 to 2026). "Chronic absence of glucagon signalling occurs in Mahvash disease, caused by a homozygous missense mutation in the GCGR, which leads to a 96% reduction in glucagon binding." (PMID 38579751, 2024). "Remarkably, α cell hyperplasia associated with inhibition of glucagon signaling is mostly reversible within 2 months after the inhibition is removed, suggesting a possible therapeutic window of opportunity for patients with Mahvash disease at the hyperplastic stage." (PMID 21853126, 2011). "In the very rare context of reduced glucagon signalling secondary to Mahvash disease, plasma glutamine, citrulline, orthinine and arginine have been noted to be elevated." (PMID 38579751, 2024). "Glucagon signalling deficiency syndromes, as exhibited by patients with Mahvash disease, GCGR−/− mice and pharmacological blockade of GCGR, are notable for very high plasma levels of glucagon and amino acids." (PMID 38579751, 2024). "Hereditary, biallelic inactivating mutations of the GCGR gene is clinically characterized by hyperglucagonemia without glucagonoma, hyperaminoacidemia, transformation of hyperplastic islets into glucagon producing microadenomas and PNET, also known as Mahvash disease." (PMID 34002801, 2021).
mental disorder (4 papers, 2018 to 2025). A disease that has its basis in the disruption of mental process. "Another hypothesis is that glucose homeostasis may cause mental disorders, regardless of the body weight; for example, the group of Bendix M. confirmed that higher insulin and lower glucagon plasma levels, are associated with SB." (PMID 29880751, 2018).
multiple sclerosis (4 papers, 2018 to 2024). A progressive autoimmune disorder affecting the central nervous system resulting in demyelination. "MAF expression has also been associated with multiple sclerosis, a range of cancers including renal cancer, glucagon expression and biosynthesis and autoimmune diabetes." (PMID 30719032, 2018). "Other comorbidities of diabetic complications, such as multiple sclerosis, β-cell mass expansion in aged mice, and glucagon action in hepatocytes, are noteworthy." (PMID 33803178, 2021).
myocardial ischemia (4 papers, 2017 to 2025). A disorder of cardiac function caused by insufficient blood flow to the muscle tissue of the heart. "Hence, our findings open the possibility that adenosine like acetylcholine offers a protection against the putative detrimental tachycardia caused by glucagon, especially in cardiac ischemia." (PMID 41516006, 2025).